TLR3 (toll like receptor 3)
Diseases named in the same sentence as TLR3 in open-access papers (continued):
Sharing a sentence is not in itself a finding about the gene and the disease.
tumor (continued). "On the other hand, TLR3 was detected at much lower levels in tumor samples displaying a low level of CAIX/HIF-1α." (PMID 27791989, 2016). "In these samples, the hypoxic markers were expressed just adjacent to the necrotic areas of the tumor, whereas TLR3 was expressed at higher levels in the periphery of the tumor, on the invasion front." (PMID 27791989, 2016). "PolyIC is an attractive anti-tumor agent, as it can induce cancer cell apoptosis by activating Toll Like Receptor 3 (TLR3) in cancer cells." (PMID 27598772, 2016). "This signaling pathway forms a TLR3/TLR4–NF-κB–HIF-1 loop that is closely associated with hypoxia and inflammation in the tumor and leads to tumor cell survival, proliferation, angiogenesis, and metastasis." (PMID 27191981, 2016). "The wide expression of TLR3 on macrophages and even on stromal cells that surround the tumour suggests an additional response from these cells upon polyI:C administration that has not yet been clearly elucidated." (PMID 27911948, 2016). "The EBERs are ligands of TLR3 and there is evidence that their stimulation supports tumor growth through an increase in insulin-like growth factor 1 (IGF-1) expression." (PMID 27791989, 2016). "In our preliminary study on a small series of 7 HNSCC samples, we found that in necrotic tumors the hypoxic markers CAIX and HIF-1α were expressed adjacent to the necrotic areas, whereas TLR3 was detected in the periphery of the tumor, on the invasion front." (PMID 27791989, 2016). "Previous studies have shown the potency of naked polyIC to induce tumor cell apoptosis through the TLR3 pathway." (PMID 27598772, 2016). "Not only a TLR3-specific (TICAM-1-dependent) signal but also TLR2 (MyD88) signal in DC triggered the expansion of CD11c+ CD8+ T cells in tumor-bearing mice." (PMID 27619885, 2016). "Poly(I:C), which is an adjuvant recognized by the pattern-recognition receptors (PRR) TLR3 and Melanoma differentiation-associated gene 5 (MDA5), acts on DCs to evoke potent CTL proliferation followed by tumor regression." (PMID 27619885, 2016). "A number of studies have emphasized the therapeutic anti-tumor potential of TLR3 stimulation by synthetic ligands." (PMID 27791989, 2016). "Collectively, the results from FACS, secondary transplantation, and gene expression profiling demonstrate that TLR3 activation significantly enhances tumor-initiating capacity and promotes CSC phenotypes in vivo." (PMID 25257174, 2015). "IHC also showed that poly I:C treatment reduced VEGF staining in LNCaP-derived tumours and angiogenesis in vivo supporting previous evidence showing that the activation of TLR3 signalling suppresses angiogenesis both in vitro and in vivo in other models 37,38." (PMID 25444175, 2015). "TLR3 agonist bacillus Calmette–Guerin (BCG) given to mice prior to tumor injection, were less likely to develop tumors than their untreated littermates and this was due to the increase in TNF." (PMID 26379664, 2015). "TLR3 was expressed more frequently in tumor tissues compared with adjacent tissues (67.1%) and tissues from subjects without HCC (80.0%)." (PMID 25884709, 2015). "In our previous study, we further demonstrated TLR3 agonists-induced activation of tumor-infiltrating NK cells and T cells leading to better tumor control." (PMID 26287667, 2015). "Our data establish a crucial role for both EBER1 and EBER2 in sustaining inflammatory signaling through TLR3 and in enriching tumor microenvironment." (PMID 26172457, 2015). "Anthracycline treated cancer cells also upregulate a TLR3/type I IFN/chemokine (C–X–C motif) ligand 10 (CXCL10) signaling cascade that results in protection from tumor growth." (PMID 26486085, 2015). "We have previously shown that the TLR3 agonists polyinosinic:polycytidylic acid (poly-IC) and polyadenylic-polyuridylic acid (poly-AU) promote control of tumor growth in the murine models of liver tumor." (PMID 26287667, 2015).
tumor (continued). "TLR3 is a key player in antiviral immunity and tumour suppression and must be tightly regulated to avoid excessive inflammation and immune response." (PMID 25938551, 2015). "The frequency of TLR3 expression in HCC tumor sections correlated positively with those of TRIF (γ = 0.322, P < 0.01), NF-κB (γ = 0.264, P < 0.05), and IRF3 (γ = 0.317, P < 0.01)." (PMID 25884709, 2015). "For instance, it has been shown that intratumoral administration of LPS can induce resistance to CTLs and drives NK cell anergy, whereas triggering of TLR3 on certain tumor cell types results in tumor growth arrest." (PMID 25682197, 2015). "TLR3 is expressed by fibroblasts, lung epithelial cells, hepatocytes, and several types of tumor cells." (PMID 25884709, 2015). "Our group has previously demonstrated that activation of TLR3 in PCa cell lines induces the secretion of cytokines and chemokines that can recruit and activate immune cells in the tumour site consequently promoting their anticancer activity." (PMID 25444175, 2015). "One of the TLR family members - TLR3 has been confirmed to be differentially expressed in NB, and predict a favorable prognosis with a high expression in tumor tissues by our group." (PMID 26208481, 2015). "EBER1 or EBER2 stable expressing B16 cells were inoculated s.c. into wild-type (WT) or TLR3 gene knock-out C57 mice and tumor growth were recorded." (PMID 26172457, 2015). "Our secondary implantation model further revealed that TLR3 agonist markedly promoted tumor growth in nude mice." (PMID 25257174, 2015). "Consistently, absolute numbers of CD44high/CD24−/low sub-population increased by 2.1-fold in SUM190-transplanted mice receiving poly(I:C) injection, demonstrating that TLR3 activation retards tumor growth but enriches for breast CSCs." (PMID 25257174, 2015). "Accordingly, we have demonstrated that TLR3 triggering can directly induce the apoptosis of TLR3-expressing tumor cells, and the expression of chemokine CXCL10 and CCL5 which promote infiltration of T cells and NK cells into the tumor." (PMID 26287667, 2015). "TLR3 is also expressed by fibroblasts, lung epithelial cells, hepatocytes, and several types of tumor cells." (PMID 25983748, 2015). "Using qPCR analysis and soft-agar colony-forming assays, we showed a significant upregulation of various stem cell markers and an increase in tumor propagating properties in vitro after treatment with TLR3 agonist poly (I:C)." (PMID 25257174, 2015). "For example, TLR4-primed MSCs have an antitumor effect, whereas TLR3-primed MSCs promote tumor growth and metastasis." (PMID 24971369, 2014). "Stimulation of TLR3+ OSCC tumor cells promoted their migration, and TLR3 expression was found to be significantly correlated with poor differentiation and perineural invasion in OSCC." (PMID 25309546, 2014). "These defined TLR signaling pathways seem difficult to help understand why the activation of some TLRs such as TLR3 inhibits tumor growth but the activation of other TLRs such as TLR2 promotes tumor growth." (PMID 25101092, 2014). "For example, co-delivery of the TLR3 agonist poly A:U induced an effective anti-tumor response when used in combination with CpG ODN under conditions when each agonist alone was ineffective." (PMID 24982761, 2014). "In tumor-bearing mice, Shime and colleagues found that activation of TLR3/Toll-IL-1 receptor domain-containing adaptor molecule 1 by Poly(I:C) rapidly induced the production of pro-inflammatory cytokines and thereafter accelerated M1 macrophage polarization." (PMID 25125485, 2014). "The administration of agents that interfered with TLR3 signaling in a mouse model of lung cancer led to tumor regression by converting tumor-supporting macrophages to tumor suppressors." (PMID 25309546, 2014). "In those, varying TLR patterns have been found not only among normal/neoplastic cells (e.g., upregulation of TLR3/4 in tumors), but also within a single tumor." (PMID 24371445, 2013).
tumor (continued). "Direct oncopathic effects on different tumor entities have been described for Poly I:C (TLR3 agonist) and Imiquimod (TLR7 agonist)." (PMID 24371445, 2013). "This is the first report to show a role for TRAIL in IL-27–mediated inhibition of tumor growth as well as a cooperative effect between IL-27 and poly(I:C) on the inhibition of tumor growth through TLR3 up-regulation by IL-27." (PMID 24155891, 2013). "When up-regulated TLR3 expression was reduced by 58% with 100 nM of its siRNA, which was determined by the intensity of each band, suppressed tumor growth was significantly recovered." (PMID 24155891, 2013). "Since TLR3 is frequently expressed by various types of malignant cells and can directly trigger tumor cell apoptosis, TLR3 is considered to be a promising target for therapeutic purpose." (PMID 24155891, 2013). "Administration of poly(I:C), a TLR3 agonist, as a tumor vaccine adjuvant was shown to selectively upregulate PD-L1 expression on mouse CD8α+ DCs." (PMID 24348481, 2013). "Tumors with high TLR3 expression by tumor cell or with high TLR4 expression by mononuclear inflammatory cells (MICs), but not TLR9 high fibroblast like cells were significantly associated with higher probability of metastasis." (PMID 22295250, 2012). "TLR3 mRNA expression in the SCC tumor center was 8.51±2.11-fold higher (p<0.01) than in normal skin and also higher than in peritumoral tissue (1.61±0.70, p<0.05)." (PMID 22808251, 2012). "Poly I:C can bind to and up-regulate TLR3 expression on some tumor cells and enhances cycloheximide-induced apoptosis via a TLR3 pathway." (PMID 22629344, 2012). "To elicit immunity against a syngeneic tumor, we used the Toll-like receptor 3 agonist polyI:C as an adjuvant." (PMID 22438914, 2012). "The fact that TLR3 is consistently expressed by NPC cells suggests that it plays a role in NPC tumour growth." (PMID 23198710, 2012). "In the present study, we investigated TLR3 expression in human NB specimens to delineate the correlation of TLR3 expression with tumor differentiation." (PMID 21861882, 2011). "TLR3 is widely expressed on tumor cells, and its signals affect a wide range of physiological and pathophysiological processes." (PMID 21737330, 2011). "The TLR3 – poly(IC)ligand possesses proapoptotic activity not only against tumor cells, but alsoagainst the cells surrounding the tumor (e.g., endothelial cells)." (PMID 22649707, 2011). "Tumors with high TLR3 expression by tumor cell or with high TLR4 expression by mononuclear inflammatory cells were significantly associated with higher probability of metastasis." (PMID 21129170, 2010). "In this study, we investigated the expression and proapoptotic activity of TLR3 in human and murine tumor cell lines." (PMID 18199340, 2008). "Blockade of TLR3 recognition with anti-TLR3 antibody greatly attenuated the proapoptotic effects of poly I:C on tumor cells cultured with CHX." (PMID 18199340, 2008). "As double-stranded RNA has also been proved to induce cell apoptosis through PKR pathway, we use antibody to block TLR3 signaling in order to prove that the poly I:C-enhanced tumor cells apoptosis is mediated by TLR3." (PMID 18199340, 2008). "In the present study, we investigated the response of tumor cell lines from different origin in vitro to the stimulation with TLR3 agonist poly I:C and the tumor chemotherapeutic drug CHX." (PMID 18199340, 2008). "RT-PCR and FACS analysis were used to detect expression of TLR3 in various human and murine tumor cell lines." (PMID 18199340, 2008). "The results showed that blockade of TLR3 recognition with anti-TLR3 antibody greatly attenuated the apoptosis-improving effects of poly I:C on tumor cells." (PMID 18199340, 2008). "Here, we extensively analyzed the expression and proapoptotic activity of TLR3 in a variety of human and murine tumor cells, and further confirmed that TLR3 are widely expressed on human and murine tumor cells." (PMID 18199340, 2008).
tumor (continued). "Notably, the TRIM3/TLR3 axis overrides this feedback inhibition through TRIM3-mediated K63-linked ubiquitination of TLR3 at K808, thereby suppressing NSCLC cell proliferation and inhibiting tumor growth." (PMID 41545343, 2026). "Conditioned media from poly(I:C)-treated LNCaP and DU145 cells recruited leukocyte subpopulations, suggesting that TLR3 activation may modulate early immune responses within the tumor microenvironment." (PMID 41601666, 2026). "The pro-tumor capabilities of TLR3 activation are not as well-characterized as their anti-tumor counterparts; however, several mechanisms have been proposed in TLR3-associated tumorigenesis leading to recurrence and metastasis." (PMID 39988665, 2025). "The activation of TLR3 helps tumor cells evade immune surveillance and promotes tumor metastasis." (PMID 40727252, 2025). "However, recent studies have shown that the increased expression of endogenous TLR3 in tumor cells can improve the responses of CD4+ Th1 and CD8+ cytotoxic T cells, and is used to improve immunotherapy by innate immunity in the TMEt." (PMID 40406122, 2025). "Conditional TLR3 knockdown abolished tumor sphere formation, confirming its important role." (PMID 40647457, 2025). "In the present study, we further explore this topic and study whether TLR3 activation can increase the expression and excretion of DAMPs from tumor cells, which can bind and induce other TLRs or similar receptors such as RAGE." (PMID 40647457, 2025). "Additionally, the tumor-derived exosomal RNAs promote lung pre-metastatic niche formation via activating TLR3, driving neutrophil infiltration and the establishment of a pre-metastatic microenvironment." (PMID 41293166, 2025). "Poly(I: C) is formed by the polymerization of inosinic acid and cytidylic acid and well known as an agonist of Toll-like Receptor 3 (TLR 3) that can stimulate tumor cells to secrete immune factors, such as IL-6 and IFN-α, and then activate the tumor immune response." (PMID 39743555, 2025). "TLR3 activation directly inhibits tumor growth in cancer cells." (PMID 40844548, 2025). "There is also one study that revealed TNF receptor-associated factor 6 (TRAF6) as a key player in tumor metastasis regulation through EMT and CSC phenotypes; however, as TRAF6 is the signaling molecule in the TLR3 signaling pathway, a similar effect can be generated with TLR3 stimulation." (PMID 40647457, 2025). "Also, strategies for identifying molecules that synergize with TLR3 as potential tumor therapeutic targets still warrants deeper exploration." (PMID 40675966, 2025). "IL-10 could inhibit excessive activation of TLR3, and the mechanism of IL-10 involves downregulation of NF-κB pathway, which alleviated inflammatory response in tumor microenvironment." (PMID 40535567, 2025). "In addition, inhibition of TLR3 also reversed the tumor-promoting effect of YTHDF2 knockdown in mice from A431 cells." (PMID 41224760, 2025). "TLR3 agonists enhance DC activation and induce tumor‐specific T cell responses." (PMID 41200280, 2025). "In contrast, TLR3 was expressed at very low levels in all cell types, especially in tumor cells." (PMID 39981252, 2025). "Furthermore, TLR3 activation through Poly I: C induces macrophage polarization towards a more tumor suppressive state in acute myeloid leukemia." (PMID 39988665, 2025). "The roles and mechanisms of key genes in Anoscore, such as S100A11 and TLR3, in biological functions, including anoikis, tumor progression, immune modulation and drug sensitivity, warrant further comprehensive investigation through in vitro and in vivo experiments." (PMID 39981252, 2025). "There are only two TLR3-expressing tumor sites: CD11b + cDC2 and CD103+ cDC1." (PMID 40727443, 2025). "In the immunotherapy, it was found that TLR3 agonists could activate the anti‐tumor immune responses based on Killer T Cells." (PMID 38738791, 2024).
tumor (continued). "Toll-like receptor 3 (TLR3) is an innate immune receptor expressed in immune cells and cancer cells that senses exogenous and endogenous endosomal double stranded RNA and is crucial in generating anti-microbial and tumor specific immune responses." (PMID 39072334, 2024). "In our study, for the first time, we assessed the impact of TLR3/4-primed-MSCs-CMs on anti-tumour activities of MSCs in a time and dose-dependent manner by focusing on induced-apoptotic components cell signalling pathways and compared MSCs phenotypes (MSC-1 and MSC-2) on the GBM cell line." (PMID 38698968, 2024). "Tumor cells exhibiting high TLR3 expression correlate with a higher likelihood of metastasis." (PMID 38903515, 2024). "Consistently with the opposite effects of CS on the inflammatory status of tumor microenvironment, TLR3 activation induced by dsRNA that is released by CS-damaged cells can boost the inflammatory microenvironment, which could promote tumor growth." (PMID 38776331, 2024). "Further investigation into TLR3 staining patterns in patient tumors could provide new approaches to understanding tumor development and aggressiveness." (PMID 39348939, 2024). "TLR-3 recognizes viral dsRNA, promotes cytokine expression, and can be pro-tumor or anti-tumor." (PMID 39335585, 2024). "Some studies have reported that the activation of TLR3 may play a divergent role in tumour progression." (PMID 38698968, 2024). "In addition to their effects on cellular components of immune microenvironment, tumor-derived exosomes were also demonstrated to activate alveolar epithelial Toll-like receptor 3 (TLR3) to recruit neutrophils, which led to formation of lung PMN." (PMID 38802766, 2024). "Considering that the expression of TLR1 signals the plasma membrane to the extracellular environment and that TLR3 is intracellular, variations in expression patterns may be related to the microenvironment and tumor development." (PMID 39208235, 2024). "TLR3/4 priming of MSCs may reprogram them toward an anti-tumour phenotype and modulate the immune-mediated killing of tumour cells by up-regulating pro-inflammatory factors." (PMID 38698968, 2024). "The Poly+5-FU combination treatment led to increased DC and CD8+ T cell infiltration in tumor tissues, supporting the hypothesis that TLR3 activation can counterbalance the immunosuppressive effects of virome depletion." (PMID 39791120, 2024). "Furthermore, in situ activation of TLR3 leads to systemic clinical tumor regression and the potentiation of the PD1 blockade." (PMID 37005579, 2023). "Similarly, activation of TLR3 by Poly(I:C) triggers a significant increase in tumor cell death, both in MNNG/HOS and RMS-CLB1." (PMID 37414800, 2023). "Finally, we showed that biomolecules triggering TLR3 activation are present in necrotic fluids derived from mouse tumor grafts and fresh tumor biopsies collected from patients." (PMID 37894949, 2023). "TLR3 agonist as an adjuvant with conventional chemotherapy can break tolerogenic or immunosuppressive effects generated by the tumor and drive T cell responses and tumor rejection." (PMID 36775056, 2023). "The influence of TLR3 expression on the tumor outcome is variable." (PMID 37894949, 2023). "Moreover, cabazitaxel is also known to promotes an inflammatory tumor microenvironment by inducing the activation of TLR3 in murine models." (PMID 37229270, 2023). "Similarly, TLR3 signaling has been found to inhibit tumor cell proliferation and promote cell apoptosis." (PMID 37781382, 2023). "In addition to the biological responses of TL-532 in cancer and normal cells, we also demonstrate that TL-532 induces anti-tumor cytokines/chemokines secretion in a TLR3-dependent manner in RAW264.7 cells." (PMID 37275475, 2023). "Furthermore, tumor-derived EVPs stimulate Toll-like receptor 3 (TLR3) activation in lung epithelial cells, which in turn initiate an inflammatory cascade and promote PMN formation." (PMID 38707985, 2023).